PAQR3 (progestin and adipoQ receptor family member 3)
Diseases named in the same sentence as PAQR3 in open-access papers (continued):
Sharing a sentence is not in itself a finding about the gene and the disease.
cancer (continued). "Among 60 collected NSCLC samples, the expression of PAQR3 mRNA in most cancer tissues was decreased significantly." (PMID 33123538, 2020). "Intriguingly, we found that PAQR3 mRNA level was robustly reduced in most of the cancer samples compared to PCHNT." (PMID 25900239, 2015). "Therefore, this study explores the roles of PAQR3 in prognosis and clinicopathological features of cancer patients through a comprehensive meta-analysis." (PMID 40391162, 2025). "The decreased expression of PAQR3 in pan-cancer might promote cancer progression and PAQR3 may be a potential therapeutic target and prognostic biomarker for cancer patients." (PMID 40391162, 2025). "Additional studies report that PAQR3 could inhibit the growth and proliferation of several cancers including esophageal cancer, gastric cancer, prostate cancer, and other cancer." (PMID 40391162, 2025). "Additionally, 5 studies reported a significant correlation between decreased expression of PAQR3 and histological grade in cancer patients (HR = 0.31, 95%CI: 0.12-0.81)." (PMID 40391162, 2025). "Therefore, we will study the function of PAQR3 in tumors and try to develop new anti-cancer drugs targeting PAQR3 to promote the development of precision therapy for tumors in the next." (PMID 38321173, 2024). "At present, the function of PAQR3 in cancers appears to be controversial." (PMID 33123538, 2020). "Therefore, strategies to restore PAQR3 expression could potentially have therapeutic benefits in cancer treatment." (PMID 37711170, 2023). "Of the 9 articles analyzed, 4 studies reported a correlation between PAQR3 levels and TNM stage (pathological stage) of cancer patients." (PMID 40391162, 2025). "Through this spatial segregation mechanism, PAQR3 effectively inhibits the sustained activation of the Ras-Raf-MEK-ERK pathway, a highly active pro-proliferative signaling cascade in most cancer cells." (PMID 40723340, 2025). "The roles of PAQR3 expression in the prognosis of patients with different types of cancer has not been fully analyzed." (PMID 40391162, 2025). "Notably, overexpression of PAQR3 has been shown to modulate ERK phosphorylation, thereby inhibiting cancer cell proliferation and invasion in LSCC." (PMID 40391162, 2025). "It reveals that DDB2 promotes the ubiquitination and degradation of a newly identified tumor suppressor PAQR3 (progestin and adipoQ receptor family member III) that limits cancer development and progression, notably inhibiting cancer cell migration, invasion, and angiogenesis." (PMID 31635251, 2019).
PAQR3 also shares sentences with these, for which no sentence is quoted: kidney (2 papers); liver cancer (2); acute myeloid leukemia (1); adenocarcinoma (1); cervical cancer (1); cholangiocarcinoma (1); endometrial carcinoma (1); esophageal squamous cell carcinoma (1); fibrosarcoma (1); gastric cardia adenocarcinoma (1); glioblastoma (1); Hepatic steatosis (1); Hyperglycemia (1); Kaposi's sarcoma (1); Lung squamous cell carcinoma (1); Lymph Node (1); neuromuscular disease (1); oropharyngeal cancer (1); prostate adenocarcinoma (1); rectum adenocarcinoma (1); renal fibrosis (1); retinopathy (1); skin cancer (1); thyroid cancer (1).